MYH9 (myosin heavy chain 9)
Diseases named in the same sentence as MYH9 in open-access papers (continued):
Sharing a sentence is not in itself a finding about the gene and the disease.
gastric cancer (41 papers, 2011 to 2025). A primary or metastatic malignant neoplasm involving the stomach. "Let-7a inhibits cell growth and tumor formation, while let-7f inhibits the invasive and metastatic potency of gastric cancer lines by downregulation of MYH9 (a metastasis-associated gene)." (PMID 23284895, 2012). "MYH9 expression is associated with poorer differentiation and prognosis, intratumoral vascular and lymphatic invasion in resected non-small cell lung cancer, and knockdown by let-7f resulted in suppression of invasion and metastasis in gastric cancer." (PMID 33330445, 2020). "Our study demonstrated that overexpression of let-7f in gastric cancer could inhibit invasion and migration of gastric cancer cells through directly targeting the tumor metastasis-associated gene MYH9." (PMID 21533124, 2011). "Our study demonstrates that Lnc21q22.11 suppresses gastric cancer cell growth by inhibiting MEK/ERK signaling pathway via the interaction with MYH9 in the nucleus." (PMID 40456011, 2025). "Further studies have demonstrated that HULC enhances proliferation, EMT, migration, and invasion of gastric cancer cells through the miR-9-5p/MYH9 axis." (PMID 40909946, 2025). "In gastric cancer, staurosporine decreases the activity of casein kinase II, leading to the reduced phosphorylation of MYH9 at the Ser1943 residue." (PMID 39273383, 2024). "The promotion of gastric cancer metastasis is facilitated by MYH9-induced expression of β-catenin in the nucleus." (PMID 39550407, 2024). "Previous studies have shown that overexpression of MYH9 lead to invasion and metastasis of gastric cancer cells." (PMID 35318312, 2022). "Previous studies have shown that MYH9 overexpression correlates with clinicopathological parameters and poor prognosis in gastric cancer and epithelial ovarian cancer." (PMID 35646686, 2022). "LncRNA HULC knockdown repressed gastric cancer progression, at least partly by regulating the miR-9-5p/MYH9 axis." (PMID 35646686, 2022). "MYH9 was also regarded as an oncogene in esophageal squamous cancer, non-small cell lung cancer, and gastric cancer." (PMID 35318312, 2022). "MYH9 has been confirmed to have vital regulatory effects in papillary thyroid cancer, osteosarcoma, gastric cancer, melanoma and other diseases." (PMID 34193158, 2021). "MYH9 has been reported to be overexpressed in gastric cancer, non-small cell lung cancer, colon cancer, and breast cancer, but was downregulated in squamous cell carcinomas." (PMID 34887392, 2021). "In this study, we uncovered that MYH9-induced CTNNB1 transcription promoted the peritoneal metastasis of gastric cancer cells." (PMID 32685004, 2020). "The overexpression of MYH9 is related to a poor prognosis in oesophageal, bladder, and gastric cancer." (PMID 30517191, 2018). "In agreement with previous reports of esophageal, bladder and gastric cancer, the present study revealed that MYH9 expression is an independent prognostic factor and associated with a poorer prognosis of patients with resected NSCLCs." (PMID 25826333, 2015). "The overexpression of MYH9 is related to a poor prognosis in esophageal, bladder, and gastric cancer." (PMID 25826333, 2015). "Liang and coworkers demonstrated that overexpression of let-7f in gastric cancer could inhibit invasion and migration of GC cells through direct targeting of the tumor metastasis-associated gene MYH9." (PMID 22408395, 2012). "In conclusion, our study demonstrates that let-7f can suppress the invasion and metastasis of gastric cancer by directly binding the 3′UTR of MYH9, its target." (PMID 21533124, 2011). "In addition, S100A4 interacts with MYH9 to promote the migration and invasion of gastric cancer cells via TGF-β-mediated EMT." (PMID 37875476, 2023).
gastric cancer (continued). "In addition, MYH9 plays a promoting role in the invasion and metastasis of gastric cancer and colorectal cancer." (PMID 36374212, 2022). "In addition, it has been reported that the activated SRF/MYH9 axis induces gastric cancer (GC) invasion and metastasis, which is related to poor outcome." (PMID 33959503, 2021). "Additionally, has-let-7f also inhibits gastric cancer invasion and metastasis through interaction with MYH9 mRNA." (PMID 34187521, 2021). "In gastric cancer (GC), MYH9-induced deubiquitination of β-catenin promotes tumor cell migration and invasion through the process of epithelial-mesenchymal transition (EMT)." (PMID 39149512, 2024). "Moreover, some studies showed that MYH9 was upregulated in gastric cancer, which could promote the transcription of β-catenin and could be upregulated in esophageal squamous cell carcinoma (ESCC) facilitating cell metastasis." (PMID 35369347, 2022). "In gastric cancer, HULC promotes cell proliferation, migration, invasion and resistance to apoptosis through the miR-9-5p/MYH9 axis." (PMID 40909946, 2025). "Astrocystin can target cytosolic MYH9-induced CTNNB1 transcription, promoting anti-apoptosis and metastasis of gastric cancer cells." (PMID 39149512, 2024). "Myosin heavy chain 9 (MYH9) has also been found to promote the transcription of catenin beta 1 (CTNNB1), thus rendering resistance to gastric cancer cells against anoikis both in vivo and in vitro." (PMID 35359956, 2022). "Recently, it was confirmed that MYH9 binds to the CTNNB1 promoter to promote CTNNB1 transcription, conferring resistance to anoikis in gastric cancer." (PMID 34887392, 2021). "The downregulated MYH9 protein impairs the recruitment of the deubiquitinase USP2, promoting the degradation of β-conjugated proteins and ultimately inhibiting EMT signaling, cell migration, invasion, and metastasis, indicating its potential as a therapeutic target in gastric cancer." (PMID 39149512, 2024).
breast carcinoma (33 papers, 2008 to 2026). "Future studies in HER2+ breast cancers would determine conditional loss of MYH9 in HER2+ breast cancer xenografts in vivo and additionally examine the efficacy of inhibitors of ROCK, upstream of NMIIA, in combination with HER2 inhibition." (PMID 37200287, 2023). "Breast cancer patients with high MYH9 were significantly associated with a shorter disease specific survival compared to patients with low MYH9 expression from the METABRIC cohort of patients." (PMID 37200287, 2023). "We identified NMIIA encoded by MYH9 as a HER3 binding protein upon pharmacological inhibition of HER2 in HER2+ breast cancer cells." (PMID 37200287, 2023). "We revealed that SIPA1 promoted the transcription of MYH9, which encodes myosin-9, and up-regulated the expression level of myosin-9 in breast cancer cells and their EVs." (PMID 35453742, 2022). "We also confirmed that effects of G3BPs’ depletion on MYH9 expression are replicated in other cell line, namely breast cancer MDA-MB-468 cells." (PMID 41542566, 2026). "Signal-induced proliferation-associated protein 1 (SIPA1) promotes the secretion of exosomes enriched with myosin heavy chain 9 (MYH9) from breast cancer cells." (PMID 40564894, 2025). "The results of these rescue experiments suggest that FATS enhances chemosensitivity to breast cancer cells by degrading MYH9, downregulating the Wnt pathway, and promoting apoptosis." (PMID 39550407, 2024). "We also performed immunofluorescence experiments and found endogenous co-localization of FATS and MYH9 in the cytoplasm of breast cancer cells." (PMID 39550407, 2024). "Subsequently, we aimed to confirm that in vivo, FATS enhances breast cancer paclitaxel chemosensitivity by degrading MYH9." (PMID 39550407, 2024). "Subsequently, animal experiments were conducted, wherein the tumor size of the mouse breast cancer model with MYH9 knockdown was observed to be smaller than that of the control group." (PMID 39550407, 2024). "By overexpressing FATS and MYH9, we demonstrated that FATS enhanced paclitaxel-induced apoptosis in breast cancer cells by degrading MYH9 to downregulate the Wnt pathway." (PMID 39550407, 2024). "This study presents a new mechanism by which FATS interacts with MYH9 to suppress the Wnt/β-catenin signaling pathway and induce apoptosis, thus enhancing the sensitivity of breast cancer cells to paclitaxel chemotherapy." (PMID 39550407, 2024). "In vitro, FATS significantly increased the inhibitory effects of paclitaxel on breast cancer cells, which were rescued by overexpressing MYH9." (PMID 39550407, 2024). "This study uncovers a new mechanism by which FATS interacts with MYH9 to counteract the Wnt pathway, thereby increasing the sensitivity of breast cancer cells to paclitaxel chemotherapy." (PMID 39550407, 2024). "In particular, we observed the upregulation of MYH9, which regulates cell polarity and cytoskeleton and has been shown to enhance cell migration in breast cancer cells." (PMID 37947594, 2023). "When it comes to the expression levels of myosin-9 in breast cancer cells, MDA-MB-231 cells showed a higher expression of myosin-9 than 231/si cells, and the mRNA expression of MYH9 in 231/si cells was significantly lower than that in MDA-MB-231 cells." (PMID 35453742, 2022). "Taken together, SIPA1 induced MYH9 transcription and up-regulated its expression at the protein level in breast cancer cells." (PMID 35453742, 2022). "We found that SIPA1 up-regulated myosin-9 levels in breast cancer cells as well as in EVs by binding to the MYH9 gene promoter." (PMID 35453742, 2022). "MYH9 is abnormally highly expressed in esophageal squamous cell carcinoma, breast cancer, epithelial ovarian cancer and acute myeloid leukemia and is associated with poor prognosis." (PMID 36175877, 2022). "In MDA-MB-231 breast cancer cells spreading on fibronectin, MYH9 is observed at the marginal spreading lamellar region of the cells." (PMID 25826333, 2015).
breast carcinoma (continued). "MYH9 was reported to be involved in the formation of lamellopodia at the leading edge of breast cancer cells." (PMID 24504141, 2014). "Recently, MYH1 and MYH9 have been identified as candidate breast cancer genes in a systematic analysis of the breast cancer genome." (PMID 18796164, 2008). "Overexpression of TMEM120B may strengthen breast cancer stemness via the β1-integrin-FAK-TAZ-mTOR signaling axis by binding to MYH9." (PMID 38504374, 2024). "The results confirmed that MYH9 acts as an independent oncogenic factor, affecting the proliferation, migration, and invasion of breast cancer cells, thereby corroborating our hypothesis and aligning with previous literature." (PMID 39550407, 2024). "Additionally, our rescue experiments demonstrated that the mechanism by which FATS regulates breast cancer sensitivity to paclitaxel chemotherapy is also achieved through the MYH9/GSK3β/β-catenin axis." (PMID 39550407, 2024). "To investigate whether FATS enhances the effect of paclitaxel on breast cancer cells by promoting the degradation of the MYH9 protein, we co-transfected FATS and MYH9 overexpression plasmids into MCF-7 and MDA-MB-231 cells." (PMID 39550407, 2024). "TMEM120B accelerated the cycling of β1-integrin and the assembling of FAs by activating the TAZ-mTOR signaling axis via binding to MYH9 through its coil-coil domain, thus strengthening proliferation and invasion, maintaining the stemness of breast cancer cells, and promoting chemoresistance." (PMID 38504374, 2024). "Moreover, SIPA1 was shown to alter glucose metabolism, leading to breast cancer progression, and to aggravate the malignancy of breast cancer by enhancing MYH9 in extracellular vesicles." (PMID 37500797, 2023). "Therefore, the knockdown of MYH9 in breast cancer cells reduced the expression of myosin-9 in both cells and EVs, leading to the suppression of macrophage migration." (PMID 35453742, 2022). "Moreover, the RFS of SIPA1high breast cancer patients with a high MYH9 expression was significantly lower than in patients with low MYH9 expression, while the RFS of BRCA patients with SIPA1low expression was not significant." (PMID 35453742, 2022). "Moreover, MYH9 promoted the invasion of breast cancer cells, and the EGF-dependent phosphorylation of MYH9 resulted in increased migration." (PMID 34887392, 2021). "Furthermore, reducing the expression of MYH9 in an invasive form of MCF-7 breast cancer cells blocked the invasive potential of these cells." (PMID 24504141, 2014). "Recently, MYH1 encoding skeletal muscle myosin heavy polypeptide 1 and MYH9 encoding non-muscle myosin heavy chain type A, were identified as candidate breast cancer genes in systematic analyses of the breast cancer genome." (PMID 18796164, 2008). "Flow cytometry also indicated that the ratio of ALDH1-positive cells elevated more than the other groups upon co-transfecting TMEM120B + MYH9.Our results indicated that the TMEM120B–MYH9 interaction may enhance breast cancer stemness by activating the β1-integrin-FAK-TAZ-mTOR signaling axis." (PMID 38504374, 2024). "Therefore, we tested whether modulating the expression level of MYH9 in breast cancer cells would affect the accumulation of myosin-9 in EVs." (PMID 35453742, 2022). "Also, MYH9 was reported to play important roles in breast cancer motility and glioma invasion." (PMID 26134617, 2015). "Consequently, we postulated that MYH9 might exert a role in breast cancer beyond that of FATS." (PMID 39550407, 2024). "To examine the role of NMIIA in HER2+ breast cancer, we modulated NMIIA levels in BT474 and MDA-MB-453 cells using doxycycline inducible shRNA targeting MYH9." (PMID 37200287, 2023). "We next sought to examine overall levels of HER3 and MYH9 mRNA and protein upon treatment with neratinib in HER2+ breast cancer cell lines." (PMID 37200287, 2023). "In conclusion, SIPA1 in breast cancer cells promoted MYH9 transcription and up-regulated the expression of myosin-9." (PMID 35453742, 2022).
breast carcinoma (continued). "Survival analysis showed that breast cancer patients with high expression of SIPA1 and MYH9 molecules had worse relapse-free survival (p = 0.028)." (PMID 35453742, 2022). "In human MCF-7 breast cancer cells, MCF-7/6 cells which have an invasive ability show a higher expression of MYH9 than MCF-A/Z cells, which are noninvasive." (PMID 25826333, 2015). "A recent report implicates MYH9 (NMHC-IIA) as a target of SRF, which contributes to invasion and metastasis in breast cancer." (PMID 21533124, 2011). "Finally, we overexpressed TMEM120B, TMEM120B-∆CCD, MYH9, MYH9-∆CCD alone or co-transfected TMEM120B + MYH9, TMEM120B-∆CCD + MYH9, and TMEM120B + MYH9-∆CCD into breast cancer cells." (PMID 38504374, 2024). "In addition, we also found a positive correlation between mRNA levels of MYH9 and SIPA1 genes in breast cancer." (PMID 35453742, 2022). "Furthermore, we found that, in breast cancer, the expression of three typical markers of TAMs (CD86, CSF1R, and CCR2) were positively correlated with SIPA1 and MYH9, respectively." (PMID 35453742, 2022). "It suggests that macrophages in breast cancer may be an important factor leading to the decreased RFS of breast cancer patients with high expression of SIPA1 and MYH9." (PMID 35453742, 2022). "Betapudiet al found that depletion of MYH9 could inhibit MLCK and Rho Kinase, as well as the depression of migration capacity of breast cancer cells." (PMID 35318312, 2022). "Many studies suggest that MYH9/NMHC-IIA has a key role in tumor cell invasive behavior.For example, the EGF-dependent phosphorylation of the myosin-IIA heavy chain has a direct role in mediating motility and chemotaxis in MDA-MB-231 human breast cancer cells." (PMID 21533124, 2011). "We treated three groups of mouse breast cancer tumor models with paclitaxel: the first group (NC) did not overexpress FATS, the second group overexpressed FATS, and the third group overexpressed FATS and MYH9." (PMID 39550407, 2024).
Nephropathy (33 papers, 2011 to 2025). A nonspecific term referring to disease or damage of the kidneys. "Given that MYH9-RD is a lifelong condition with potential for late-onset systemic complications such as nephropathy, hearing loss, and cataract, a multidisciplinary follow-up plan is critical, even in asymptomatic pediatric patients." (PMID 41300679, 2025). "The association, incidence, and prevalence of nephropathy in MYH9-related disorders are understudied." (PMID 39588168, 2024). "More so, nephropathy associated with mutation of the MYH9 gene usually progresses to terminal CKD around the age of 30 years, yet cases of more advanced age have been described." (PMID 32765897, 2020). "The spectrum of MYH9-associated nephropathy is such that MYH9 risk variants exhibit the most remarkable relationship with every common complex kidney disease identified." (PMID 32765897, 2020). "We reported that MYH9-related nephropathy due to heterozygous MYH9 mutation manifests as global sclerosis, mild tubular atrophy, interstitial fibrosis, and proteinuria because of the foot process effacement of renal podocytes." (PMID 31118506, 2019). "MYH9 SNPs and haplotypes are associated with a risk for T2D and non-T2D nephropathy, lupus nephritis, hypertensive nephropathy, and FSGS." (PMID 31534799, 2019). "For example, MYH9 gene polymorphisms are associated with cerebrovascular disease or nephropathy in patients with diabetes." (PMID 27437869, 2017). "Our results demonstrate a likely contribution of MYH9 variant rs11089788 in the progression of CKD when co-inherited with CFHR5 nephropathy, but cast doubt on the recently alleged association with variation in the APOL1 gene that is closely linked to MYH9." (PMID 23516419, 2013). "Evidence for association with “Severe” progression in CFHR5 nephropathy was found with MYH9 variant rs11089788 and was confirmed in an independent FH cohort, D (cumulative p value = 0.001, odds ratio = 3.06, recessive model)." (PMID 23516419, 2013). "Fine mapping studies reveal that several independent SNPs and regions in and near the apolipoprotein L1 gene (APOL1) and non-muscle myosin heavy chain 9 gene (MYH9) are associated with nephropathy susceptibility." (PMID 21698141, 2011). "Herein, we scanned the genome to detect polymorphisms mediating risk for T2DM-ESRD, conditional on APOL1 G1/G2 nephropathy risk variants and the MYH9 E1 risk haplotype using case-control and case-only study designs." (PMID 21698141, 2011). "Here, the MYH9 E1 haplotype was both an important predictor and clarifier of the contribution of other loci to the risk of nephropathy." (PMID 21698141, 2011). "The strong association observed between variants in APOL1 and near the MYH9 gene with several kidney diseases was a major breakthrough in our understanding of nephropathy susceptibility in AA." (PMID 21698141, 2011). "In this report, we present two cases of MYH9-RD-associated nephropathy." (PMID 39588168, 2024). "MYH9-RD is clinically characterized by congenital macrothrombocytopenia, granulocyte inclusions variably associated with the risk of developing progressive sensorineural deafness, cataracts and nephropathy." (PMID 31977897, 2020). "In previous studies, MYH9 variants have been shown to be predictive for kidney function in the general adult population as well as in progression of primary or secondary nephropathies." (PMID 32873246, 2020). "Furthermore, HIV associated nephropathy is strongly linked to MYH9 polymorphism in African Americans." (PMID 23285077, 2012). "Therefore, the search for additional nephropathy susceptibility loci in AAs, conditional on other important loci (MYH9 and APOL1) remains critical." (PMID 21698141, 2011). "Finally, we provide functional evidence in vivo that the G2-altered APOL1 may be interacting with MYH9 to confer nephropathy risk." (PMID 26147622, 2015). "At this time, treatment of CKD progression secondary to MYH-9-related nephropathy is limited in study." (PMID 39588168, 2024).